UBE2V1 (ubiquitin conjugating enzyme E2 V1)
Description:
Has no ubiquitin ligase activity on its own. The UBE2V1-UBE2N heterodimer catalyzes the synthesis of non-canonical poly-ubiquitin chains that are linked through Lys-63. This type of poly-ubiquitination activates IKK and does not seem to involve protein degradation by the proteasome. Plays a role in the activation of NF-kappa-B mediated by IL1B, TNF, TRAF6 and TRAF2. Mediates transcriptional activation of target genes. Plays a role in the control of progress through the cell cycle and differentiation. Plays a role in the error-free DNA repair pathway and contributes to the survival of cells after DNA damage. Promotes TRIM5 capsid-specific restriction activity and the UBE2V1-UBE2N heterodimer acts in concert with TRIM5 to generate 'Lys-63'-linked polyubiquitin chains which activate the MAP3K7/TAK1 complex which in turn results in the induction and expression of NF-kappa-B and MAPK-responsive inflammatory genes. Together with RNF135 and UBE2N, catalyzes the viral RNA-dependent 'Lys-63'-linked polyubiquitination of RIGI to activate the downstream signaling pathway that leads to interferon beta production. UBE2V1-UBE2N together with TRAF3IP2 E3 ubiquitin ligase mediate 'Lys-63'-linked polyubiquitination of TRAF6, a component of IL17A-mediated signaling pathway.
Synonyms: UEV-1; CROC1; UBE2V; UEV1; CROC-1; UEV1A; CIR1
Tractability: PROTAC: ubiquitination databases record sites on it; its protein half-life has been measured; a small molecule that binds it is known.
Gene: Protein-coding gene on chromosome 20 (50,081,122 to 50,115,959, reverse strand). Ensembl gene ENSG00000244687.
Subcellular location: Nucleus
Subcellular location (Human Protein Atlas): Nucleoplasm
Pathways (Reactome):
Immune System: Antigen processing: Ubiquitination & Proteasome degradation; CLEC7A (Dectin-1) signaling; Downstream TCR signaling; FCERI mediated NF-kB activation; IKK complex recruitment mediated by RIP1; IRAK1 recruits IKK complex; IRAK1 recruits IKK complex upon TLR7/8 or 9 stimulation; Interleukin-1 signaling; JNK (c-Jun kinases) phosphorylation and activation mediated by activated human TAK1; NOD1/2 Signaling Pathway; TAK1-dependent IKK and NF-kappa-B activation; TICAM1, RIP1-mediated IKK complex recruitment; TRAF6 mediated IRF7 activation in TLR7/8 or 9 signaling; activated TAK1 mediates p38 MAPK activation
Autophagy: Aggrephagy; PINK1-PRKN Mediated Mitophagy
Disease: SARS-CoV-2 activates/modulates innate and adaptive immune responses
Gene Ontology:
Molecular function: protein binding
Biological process: positive regulation of canonical NF-kappaB signal transduction; positive regulation of intracellular signal transduction; positive regulation of protein K63-linked ubiquitination; protein K63-linked ubiquitination; cell differentiation; positive regulation of DNA-templated transcription; protein polyubiquitination; regulation of DNA repair; regulation of DNA-templated transcription
Cellular component: cytoplasm; cytosol; extracellular exosome; nucleoplasm; protein-containing complex; UBC13-MMS2 complex; ubiquitin conjugating enzyme complex; ubiquitin ligase complex; nucleus
Genetic constraint (gnomAD): Loss-of-function variants: 12 observed, 17.23 expected, observed/expected ratio (o/e) 0.7, 90% interval 0.44 to 1.13. The upper end of that interval is the gene's LOEUF score, 1.13, which puts it in group 4 of 6, group 1 being the genes least tolerant of losing a copy. Missense variants: 105 observed, 177.12 expected, observed/expected ratio (o/e) 0.59, 90% interval 0.5 to 0.7. Synonymous variants: 51 observed, 56.68 expected, observed/expected ratio (o/e) 0.9, 90% interval 0.72 to 1.14.
Homologues: Orthologues: dog UBE2V1 (100% identical), tropical clawed frog ube2v1 (95% identical), mouse Ube2v1 (94% identical). Paralogues in human: UBE2V2 (87% identical), UBE2A (28% identical), UBE2O (28% identical), UBE2T (28% identical), UBE2B (27% identical), CDC34 (26% identical), UBE2K (26% identical), UBE2N (26% identical), UBE2C (25% identical), UBE2R2 (25% identical), PEDS1 (24% identical), UBE2J1 (24% identical), and 12 more.